MYPN (myopalladin)
Description:
Component of the sarcomere that tethers together nebulin (skeletal muscle) and nebulette (cardiac muscle) to alpha-actinin, at the Z lines.
Synonyms: MYOP; CMD1DD; CMH22; CMYO24; CMYP24; NEM11; RCM4
Tractability: Antibody: its Gene Ontology location is reachable by antibodies, with medium confidence. PROTAC: ubiquitination databases record sites on it.
Gene: Protein-coding gene on chromosome 10 (68,087,897 to 68,212,017, forward strand). Ensembl gene ENSG00000138347.
Subcellular location: Cytoplasm; Nucleus; Cytoplasm, myofibril, sarcomere; Cytoplasm, myofibril, sarcomere, Z line
Subcellular location (Human Protein Atlas): Nucleoplasm; Cytosol; Vesicles
Gene Ontology:
Molecular function: cytoskeletal protein binding; muscle alpha-actinin binding; protein binding; SH3 domain binding; cell-cell adhesion mediator activity
Biological process: sarcomere organization; axon guidance; dendrite self-avoidance; homophilic cell-cell adhesion
Cellular component: cytoplasm; cytosol; I band; nucleoplasm; nucleus; Z disc; axon; plasma membrane; sarcomere
Genetic constraint (gnomAD): Loss-of-function variants: 58 observed, 121.16 expected, observed/expected ratio (o/e) 0.48, 90% interval 0.39 to 0.6. The upper end of that interval is the gene's LOEUF score, 0.6, which puts it in group 2 of 6, group 1 being the genes least tolerant of losing a copy. Missense variants: 1,537 observed, 1,669.2 expected, observed/expected ratio (o/e) 0.92, 90% interval 0.88 to 0.96. Synonymous variants: 614 observed, 619.6 expected, observed/expected ratio (o/e) 0.99, 90% interval 0.93 to 1.06.
Gene-disease validity (ClinGen):
ClinGen rates the evidence that MYPN causes each of these diseases.
MYPN-related myopathy (autosomal recessive): Definitive. Congenital myopathy caused by pathogenic mutations in MYPN that lead to a wide spectrum of phenotypes.
dilated cardiomyopathy 1KK (autosomal dominant): Limited.
hypertrophic cardiomyopathy (autosomal dominant): Disputed. A condition in which the myocardium is hypertrophied without an obvious cause.
Homologues: Orthologues: chimpanzee MYPN (99% identical), macaque MYPN (98% identical), dog MYPN (93% identical), rabbit MYPN (92% identical), pig MYPN (89% identical), guinea pig MYPN (88% identical), mouse Mypn (88% identical), rat Mypn (87% identical), tropical clawed frog mypn (59% identical), Caenorhabditis elegans unc-22 (27% identical), Drosophila melanogaster bt (16% identical), Caenorhabditis elegans dim-1 (6% identical). Paralogues in human: PALLD (37% identical), SPEG (25% identical), HMCN1 (24% identical), OBSCN (22% identical), ALPK3 (16% identical), IGFN1 (15% identical), MYOT (12% identical), CCDC141 (11% identical), SPEGNB (5% identical).
Diseases named in the same sentence as MYPN in open-access papers:
MYPN is named in the same sentence as 25 diseases in open-access papers, as found by Europe PMC text mining. Sharing a sentence is not in itself a finding about the gene and the disease. The quoted sentences say what the papers report.
cardiomyopathy (14 papers, 2018 to 2026). A disease of the heart muscle or myocardium proper. "Background/Objectives: Variants of MYPN, encoding a sarcomeric protein myopalladin, are associated with different types of cardiomyopathies and myopathies." (PMID 42074575, 2026). "PTVs in three genes with limited or moderate evidence for Mendelian cardiomyopathy were nominally associated with DCM in GeL (MYPN: OR = 15.0, P = 0.03; PRDM16: OR = 40.3, P = 0.008) and with HCM in UKB (NEXN: OR = 24.1, P = 0.01)." (PMID 39572783, 2024). "In contrast to cardiomyopathy-associated heterozygous MYPN variants, homozygous or bi-allelic truncating variants in MYPN are linked to myopathy, particularly to cap myopathy and NM." (PMID 33802723, 2021). "Variants in the MYPN gene that have been previously reported in individuals with myopathy or cardiomyopathy." (PMID 33802723, 2021). "Autosomal recessive MYPN mutations have been reported in only six families showing a mildly progressive nemaline or cap myopathy with cardiomyopathy in some patients." (PMID 31133047, 2019). "MYPN gene mutations are associated with human cardiomyopathies, whereas the role of PALLD in the heart has remained unknown, partly due to embryonic lethality of PALLD knockout mice." (PMID 36927816, 2023). "Mutations in the sarcomeric component MYOPALLADIN (encoded by MYPN) causes several cardiomyopathies and a congenital form of slowly progressing nemaline myopathy with myofibre size variation and evident atrophy termed Nemaline Myopathy 11, Autosomal Recessive (NEM11; OMIM: 617336)." (PMID 34740639, 2022). "The essential role of MYPN for normal cardiac function is supported by the identification of an increasing number of heterozygous mutations in the MYPN gene associated with various types of human cardiomyopathy, including hypertrophic (HCM), dilated (DCM), and restrictive (RCM) cardiomyopathy." (PMID 34558411, 2021). "Based on its similarity to MYPN, associated with different forms of cardiomyopathy, as well as high expression levels of specific PALLD isoforms in cardiac muscle both during development and at adult stage, we hypothesized that PALLD plays an important role also in the heart." (PMID 36927816, 2023). "Thus, the cardiomyopathy-associated MYPN mutations are thought to have dominant negative effects." (PMID 34558411, 2021). "Furthermore, two truncating MYPN variants have been associated with cardiomyopathies." (PMID 33802723, 2021). "This review will focus on six key Z-disc proteins: α-actinin 2, filamin C, myopalladin, myotilin, telethonin and Z-disc alternatively spliced PDZ-motif (ZASP), which have all been linked to myopathies and cardiomyopathies." (PMID 33802723, 2021). "Some genes are specific to one class of cardiomyopathy like RBM20 in DCM, whereas others like MYPN and TNNI3 are implicated in at least 3 different types of cardiomyopathy." (PMID 30764827, 2019). "Two interesting heterozygous deletions were found in genes (MYPN-patient XV and CSRP3-patient XVI) associated with a dominant cardiomyopathy." (PMID 30373198, 2018). "Although MYPN and CSRP3 may have a role in the observed cardiomyopathies, the primary genetic cause of the skeletal muscle disorder in these patients remains to be identified." (PMID 30373198, 2018). "However these results do not explain the association of Myopalladin mutations with various types of cardiomyopathy, including DCM, HCM, and RCM." (PMID 30764827, 2019).
nemaline myopathy (8 papers, 2017 to 2022). Nemaline myopathy (NM) encompasses a large spectrum of myopathies characterized by hypotonia, weakness and depressed or absent deep tendon reflexes, with pathologic evidence of nemaline bodies (rods) on muscle biopsy. "Biallelic loss-of-function mutations in MYPN have recently been identified in patients with nemaline myopathy, cap myopathy, and congenital myopathy with hanging big toe, some of which had mild cardiac involvement." (PMID 34558411, 2021). "A recently recognized genetic cause of nemaline myopathies is due to mutations in MYPN gene encoding for myopalladin, a multifunctional protein found at the cardiac and skeletal muscle sarcomeric Z- and I-bands and in the nucleus." (PMID 32456280, 2020). "Four patients in four families were recently described with a mild childhood-to adult onset slowly progressive nemaline myopathy with intranuclear rods and cardiac problems caused by biallelic mutations in myopalladin (MYPN)." (PMID 31133047, 2019). "Biallelic mutations of MYPN are associated with a slowly progressive nemaline myopathy and a recessive cap myopathy." (PMID 30373198, 2018). "The recessively inherited MYPN-associated nemaline myopathy is histologically characterized by the presence of intranuclear rods, which may be also observed in ACTA1 mutations and in patients with SLONM." (PMID 32456280, 2020). "Heterozygous MYPN gene mutations are associated with hypertrophic, dilated, and restrictive cardiomyopathy, and homozygous loss‐of‐function truncating mutations have recently been identified in patients with cap myopathy, nemaline myopathy, and congenital myopathy with hanging big toe." (PMID 31647200, 2020). "Cardiac involvement is rare in patients with nemaline myopathy, but has been identified in a few patients with defects in ACTA1, MYPN or MYO18B." (PMID 31228046, 2019). "We did not include the very recently reported myopalladin gene (MYPN) in our gene panel, which in case of mutations was shown to cause nemaline myopathy as well." (PMID 28490364, 2017).
dilated cardiomyopathy (5 papers, 2017 to 2023). Cardiomyopathy which is characterized by dilation and contractile dysfunction of the left and right ventricles. "MYPN has been described to be associated with both hypertrophic and dilated cardiomyopathy (DCM), although their association is still considered to be limited." (PMID 36293497, 2022). "For example, mutations in JUP, DSP, PKP2, DSG2, DSC2, CTNNA3, CDH2, or PLN (all of them more abundant in LV) predominantly lead to arrhythmogenic right ventricular cardiomyopathy, and mutations in MYH7, HSPB7, NEXN and MYPN (also all more abundant in LV) lead to dilated cardiomyopathy." (PMID 32291283, 2020). "Variants in MYPN have previously been implicated in dilated cardiomyopathy, not a clinical finding in our patients, and although rare (allele count 69/121208), there are 2 homozygotes noted in ExAC for this variant." (PMID 28165343, 2017). "(C) Quantitative real-time PCR (qRT-PCR) analysis for MYPN, PALLD, and ANKRD1 on LV biopsies from dilated cardiomyopathy (DCM) (n = 15) and ischemic cardiomyopathy (ICM) (n = 15) male patients vs." (PMID 36927816, 2023).
restrictive cardiomyopathy (5 papers, 2017 to 2021). A type of heart disorder referring to the inability of the ventricles to fill with blood because the myocardium (heart muscle) stiffens and looses its flexibility. "Heterozygous variants in MYPN have been associated with different cardiac phenotypes: dilated, hypertrophic, or restrictive cardiomyopathy, even if some reports should be reanalyzed." (PMID 31133047, 2019). "Autosomal dominant MYPN mutations cause hypertrophic, dilated, or restrictive cardiomyopathy." (PMID 31133047, 2019). "Restrictive cardiomyopathy is a rare cardiac disease, for which several genes including TNNT2, MYPN, FLNC and TNNI3 have been associated with its familial form." (PMID 30953456, 2019). "MYPN gene mutations are causative for dilated (DCM), hypertrophic, and restrictive cardiomyopathy." (PMID 34558411, 2021). "Also, the mutations in MYPN were linked with DCM, HCM and restrictive cardiomyopathy (RCM)." (PMID 28427417, 2017).
hypertrophic cardiomyopathy (4 papers, 2017 to 2026). "Specifically, an MYPN deletion was found in patient XV presenting with hypertrophic cardiomyopathy and centronuclear myopathy." (PMID 30373198, 2018).
congenital myopathy (3 papers, 2019 to 2021). "Z line streaming and thickening or nemaline rods have been described in the muscle of patients with MYPN mutations, and both alterations may be found in patients with recessive slowly progressive congenital myopathy." (PMID 31133047, 2019). "Here, we described a congenital myopathy with hanging big toe and cardiac involvement due to a novel homozygous MYPN mutation resulting in myopalladin deficiency and in a peculiar ultrastructural stretching of Z line." (PMID 31133047, 2019). "Here, we described a congenital myopathy with hanging big toe and cardiac problems due to a novel homozygous MYPN mutation resulting in myopalladin deficiency and in a peculiar ultrastructural disruption of the regular square pattern of the Z line, but no nemaline or caps on muscle pathology." (PMID 31133047, 2019).
Insulin resistance (1 paper, 2019). Increased resistance towards insulin, that is, diminished effectiveness of insulin in reducing blood glucose levels. "MYPN is novel biomarker for the development of insulin resistance." (PMID 30678306, 2019).
ischemic cardiomyopathy (1 paper, 2023). Ischemic cardiomyopathy is a cardiomyopathy in which a weakness in the muscle of the heart due to inadequate oxygen delivery to the myocardium with coronary artery disease being the most common cause. "Quantitative real-time PCR (qRT-PCR) analyses on myocardial tissue from DCM and ischemic cardiomyopathy (ICM) patients showed increased transcript levels of MYPN and the PALLD long isoform in DCM patients, while total transcript levels of PALLD were reduced in both DCM and ICM patients." (PMID 36927816, 2023). "Altered transcript levels of MYPN and PALLD isoforms were found in myocardial tissue from human dilated and ischemic cardiomyopathy patients, whereas their protein expression levels were unaltered." (PMID 36927816, 2023). "Similarly, in two RNA-Seq studies, PALLD was reported to be downregulated in both DCM/non-ischemic cardiomyopathy (NICM) (~1.7- to ~2.0-fold) and ICM (~1.6- to ~2.1-fold) patients, while MYPN was upregulated in both DCM/NICM (~1.5- to ~1.6-fold) and ICM (~1.6- to ~1.7-fold) patients." (PMID 36927816, 2023).
myopathy (6 papers, 2019 to 2026). A disease of the muscle in which the muscle fibers do not function properly. "Homozygous truncating mutations in MYPN were subsequently reported in other two families, in which three patients presented with a slowly progressive cap myopathy characterized by facial, axial, hip-girdle, and distal weakness, but not cardiac alterations." (PMID 31133047, 2019). "Our family further broadens the clinical spectrum of MYPN-related myopathies." (PMID 31133047, 2019).
cardiac disease (3 papers, 2019 to 2024). "However, as for MYPN, whose ablation does not severely affect cardiac function, it is possible that mutations with dominant negative effects may be linked to cardiac disease." (PMID 36927816, 2023). "Our findings demonstrating an important role of PALLD for normal cardiac function prompted us to determine whether transcript levels of PALLD and its striated muscle-specific homologue MYPN are altered during ischemic and nonischemic cardiac disease." (PMID 36927816, 2023).
tumour (1 paper, 2020). "Missense variants were found in MYPN, SERPINB8 (SPB8) and ESYT2, which were among the top ten most upregulated proteins in the tumour group." (PMID 33048956, 2020).
MYPN also shares sentences with these, for which no sentence is quoted: cap myopathy (5 papers); muscular dystrophies (2); short QT syndrome (2); Arrhythmia (1); atrial fibrillation (1); centronuclear myopathy (1); COVID-19 (1); intrinsic cardiomyopathy (1); Nemaline Myopathy 11, Autosomal Recessive (1); neuromuscular genetic disease (1); Right ventricular cardiomyopathy (1); skeletal muscle disorder (1); Ventricular arrhythmia (1); ventricular fibrillation (1).